SIRT1 (sirtuin 1)
Diseases named in the same sentence as SIRT1 in open-access papers (continued):
Sharing a sentence is not in itself a finding about the gene and the disease.
cancer (continued). "However, data on the exact role of SIRT1 in cancer remain contradictory, with some studies suggesting context-specific effects that include both pro-tumorigenic and tumor-suppressive actions." (PMID 39409979, 2024). "Furthermore, increased expression of SIRT1 has been found to confer resistance to cisplatin in cancer cells." (PMID 38828455, 2024). "Similarly, the downregulation of miR-212 correlates with enhanced SIRT1 activity, thereby facilitating starvation-induced autophagy and promoting angiogenesis and cellular senescence in cancer cells." (PMID 39796040, 2024). "Therefore, increasing evidences highlight the function of SIRT1 in the regulation of cancer progression and interaction with various molecular pathways (Wang XW." (PMID 39403142, 2024). "Furthermore, c-MYC potentially enhances the activation of SIRT1 by directly binding to the SIRT1 inhibitor Deleted in Breast Cancer 1 (DBC1) and blocking its interaction with SIRT1." (PMID 38397988, 2024). "Although the diverse functions of SIRT1 in cancer remain unclear and contradictory, the activation of SIRT1 pathways may lead to a range of beneficial therapeutic effects for cancer." (PMID 39683482, 2024). "Sirt6 exhibits anti-cancer effects in many malignancies; however, whether Sirt1 acts as a pro-tumorigenic or anti-tumorigenic factor remains unclear." (PMID 38254877, 2024). "Among the cytosolic deacetylases responsible for the deacetylation of nonhistone proteins (i.e., HDAC6, SIRT1, and SIRT2), the expression of SIRT1/2 was considerably higher in cancer cells (i.e., A549 and HCC1806 cells) than in normal tissue cells (i.e., BEAS-2B and HMLE cells)." (PMID 38649663, 2024). "The function of SIRT1 in cancer cells is extremely complicated." (PMID 38539819, 2024). "SIRT1 silencing exhibits anti-cancer effects in the initiation and progression of HCC." (PMID 38044396, 2024). "Furthermore, SIRT1 upregulation was reported in numerous human cancers, including melanoma, colon, prostrate, breast, liver, lymphoma, leukemia, and sarcomas." (PMID 39683482, 2024). "Additionally, we identified the common mutation types and sites of SIRT1, constructed its PPI network, and analyzed its role in key cancer pathways." (PMID 39845948, 2024). "The findings revealed that in 33 cancers, SIRT1 was positively correlated with the levels of eosinophils, T helper cells, central memory T cells (Tcm), effector memory T cells (Tem), γδ T cells (Tgd), and Th2 cell infiltration and negatively correlated with most other immune cell types." (PMID 39845948, 2024). "In addition to its expression in immune subtypes, our analysis revealed that SIRT1 was significantly differentially expressed in molecular subtypes of multiple cancers, such as BRCA, COAD, and ESCA." (PMID 39845948, 2024). "Through bioinformatics analysis, we comprehensively evaluated the function of SIRT1 in pan-cancer." (PMID 39845948, 2024). "SIRT1 mRNA expression in multiple cancer types was evaluated via the TCGA and GTEx databases." (PMID 39845948, 2024). "In summary, these findings reveal the important role of SIRT1 in the prognosis of multiple cancers, but its function in different cancers may differ." (PMID 39845948, 2024). "Interestingly, tNOX knockdown was reported to partially attenuate SIRT1 expression and repressed growth in various cancer cell types, such as lung, bladder, and stomach." (PMID 38567911, 2024). "Hence, targeting the epigenetic modifiers of c-Myc or SIRT1 is regarded as a good strategy for effective cancer therapy." (PMID 38673833, 2024). "Similarly, a 9–16 % increase in mouselifespan was achieved by triggering transgenic SIRT1 specificallyin hypothalamic cells, whereas inan earlier study, an overexpression of SIRT1 in mice did notaffect longevity, although it reduced the likelihood of cancer." (PMID 38680178, 2024).
cancer (continued). "Also, it is noteworthy that SIRT1 has been considered as a target of several diseases such as aging, cancer, autoimmune disease and obstructive pulmonary disease." (PMID 38673833, 2024). "A notable aspect of SIRT1-mediated autophagy is its role in various human cancers." (PMID 39403142, 2024). "Sirtuins, a family of NAD+-dependent deacetylases (SIRT1-7), play diverse roles in tumor progression, with certain isoforms acting as tumor suppressors, while others promote tumorigenesis, positioning them as potential targets for cancer therapy." (PMID 39796040, 2024). "In this regard, SIRT1 has been shown to silence specific tumor suppressor genes in prostate cancer cells, while it is upregulated in the nucleus and also in the cytoplasm of cancer cells." (PMID 39497715, 2024). "SIRT1’s modulation of DNA repair and tumor-suppressing genes, combined with its inhibition of oncogenes and oncoproteins, can lead to it having a protective role against cancer." (PMID 39683482, 2024). "Inducers of SIRT1, such as resveratrol and other small molecules, have been shown to activate SIRT1’s deacetylase activity, which leads to the suppression of tumor progression through the inhibition of cancer cell proliferation and the promotion of apoptosis." (PMID 39403142, 2024). "Therefore, the combined application of cisplatin and SIRT1 inhibitors offers promising prospects for developing novel cancer chemotherapy strategies." (PMID 38741782, 2024). "Therefore, SIRT1 not only serves as a potential therapeutic target but also as a valuable biomarker for early cancer diagnosis." (PMID 39845948, 2024). "Therefore, identifying the cancer-specific roles of SIRT1 and tailoring the application of its inducers and inhibitors is critical for developing precise and effective cancer therapies." (PMID 39403142, 2024). "In addition, the latest research reports that sirtuin 1 (SIRT1) deficiency induces WEE1 hyperacetylation and activation, rendering cancer cells resistant to WEE1 inhibition." (PMID 38231277, 2024). "SIRT1 expression is significantly different in different cancer molecular and immune subtypes." (PMID 39845948, 2024). "Similarly, the suppression of miR-449a in ERG-positive PCa elevates SIRT1 expression, creating a feedback loop involving ERG, miR-449a, and SIRT1, which drives invasive cancer phenotypes." (PMID 39796040, 2024). "Also, the silent information regulator sirtuin 1 (SIRT1) protein is known as a post-translational regulator that is involved in inflammation and cancer progression." (PMID 38673833, 2024). "Therefore, targeting SIRT1 with anticancer drugs or other therapies is a possible strategy to eliminate cancer cells." (PMID 38539819, 2024). "SIRT1 inducers are of particular interest in cancers where SIRT1 functions as a tumor suppressor." (PMID 39403142, 2024). "Furthermore, we explored the correlation between SIRT1 expression and immune cell infiltration across 33 different types of cancer." (PMID 39845948, 2024). "The capacity of SIRT1 to enhance cell viability and mitigate apoptotic signals, as demonstrated by compounds like 19e, further emphasizes its role in protecting pancreatic beta-cells and cancer cells under stress conditions." (PMID 39682281, 2024). "Using an integrative approach involving bioinformatics analysis and experimental validation, we clarified the potential roles and mechanisms of SIRT1 in pan-cancer, providing a theoretical basis for the development of SIRT1-targeted therapies in clinical applications." (PMID 39845948, 2024).
cancer (continued). "Further analyses of RNA sequencing (RNA-Seq) data from 1404 cancer cell lines across 28 cancer types and proteomic data from 375 cancer cell lines across 21 cancer types from the CCLE database revealed similar mRNAs and protein expression levels of ISG15 and SIRT1 in various cancer cell lines." (PMID 38443596, 2024). "By contrast, associations of stronger upregulation of SIRT1, SIRT2, and SIRT5 with sensitivity to dasatinib were unexpected, since previous studies had reported benefits of their downregulation or depletion in improving cancer outcomes." (PMID 38369747, 2024). "In addition, a significant role in various facets of cancer drug resistance has recently been attributed to Sirt1." (PMID 37958610, 2023). "Treatment of mice with the SIRT1 inhibitor tenovin-6 prevents cancer progression." (PMID 36843938, 2023). "Furthermore, a shift in the subcellular localization of SIRT1 from the nucleus to the cytoplasm was observed in less differentiated malignant tumors." (PMID 37627400, 2023). "The role of SIRT1 in cancer varies depends on its location and cell type." (PMID 38006398, 2023). "Sirtuin‐1 (SIRT1) which known as a histone deacetylase has already been demonstrated to be involved in autophagy, apoptosis, senescence, genome stability maintenance in cancer through multiple approaches." (PMID 36510377, 2023). "SIRT1 has recently been given increasing attention in muscle function, muscle physiology, balancing muscle cell differentiation, and proliferation, especially in cancer cachexia-induced muscle atrophy." (PMID 37190306, 2023). "Therefore, we thought that increased SIRT1 expression has a promoting role in KRASMut cancer by reducing the acetylation of KRASMut, which results in the activation of KRASMut." (PMID 37779142, 2023). "Consequently, SIRT1 inhibitors have exhibited promising anti-cancer effects in animal models of cancer." (PMID 38117829, 2023). "Regarding the roles of the SIRT1-c-Myc axis in supporting cancer stem cell maintenance." (PMID 37960146, 2023). "Today, SIRT1 is targeted in many age-related human pathologies, such as cardiovascular disease, diabetes and other metabolic syndromes, chronic inflammation, neurodegenerative disorders, and cancer." (PMID 37715252, 2023). "Additionally, as we demonstrated, SIRT1 has been proposed as a key regulator of cancer metastasis that promotes EMT and is involved in various signaling pathways related to carcinogenesis." (PMID 37490168, 2023). "SIRT1 inhibition increased the frequency of initiation and triggered initiation from a group of origins that were dormant in untreated cells, similar to the activation observed in cancer cells." (PMID 37998365, 2023). "By elucidating the role of SIRT1 in safeguarding rDNA integrity, these findings may have broader implications for therapeutic approaches targeting SIRT1 in the context of aging and cancer." (PMID 37998365, 2023). "In the tumor and cancer-specific context, SIRT1 activation or inhibition provides a better therapeutic approach with critical insights into understanding the molecular involvement and aspects of SIRT1 regulating small-molecular drug candidates." (PMID 37949849, 2023). "Furthermore, several studies have found that the content of SIRT1 decreased significantly in the course of cancer cachexia." (PMID 37190306, 2023). "Accumulating evidence has recently revealed that SIRT1 may act as a tumor suppressor in several types of cancer, thus, activating SIRT1 would represent a possible therapeutic strategy." (PMID 37100462, 2023). "It has been reported that SIRT1 modulates cell proliferation, survival and senescence, while also establishing a complex interaction with FOXOs, thus affecting clinical conditions such as cancer." (PMID 37242544, 2023).
cancer (continued). "Here, we report the effects of chronological aging and SIRT1 activity on R-loop levels and replication origin usage in normal fibroblasts obtained at different time points during chronological aging, as well as in cancer cells." (PMID 37998365, 2023). "However, the specific function of hepatic SIRT1 in metabolism and cancer is still not fully understood." (PMID 37715252, 2023). "SIRT1 functions as a dual regulator of survival and cell death induction in cancer cells." (PMID 37949849, 2023). "In addition, propofol downregulated SIRT1 in cancer and inhibited the Wnt/β-catenin pathway and PI3K/AKT/mTOR pathway." (PMID 37490168, 2023). "The silent information regulator sirtuin 1 (SIRT1) protein is a histone deacetylase, which links the metabolic state of cells with the regulation of gene expression and many processes related to cancer (such as apoptosis, oxidative stress, neuronal autophagy, immune response and so on)." (PMID 37742223, 2023). "Mechanistically, UA inhibited inflammatory responses, decreased the concentration of cytokines in serum, and alleviated symptoms of cancer cachexia via activating SIRT1, thence downregulating the ubiquitin E3 ligase expression levels and the phosphorylation of NF-κB and STAT3." (PMID 37190306, 2023). "Both SIRT1 and HDAC1 have been implicated in cancer development." (PMID 37667739, 2023). "SIRT1 is extensively studied in the context of cancer as well." (PMID 37100462, 2023). "SIRT1 can either promote or inhibits EMT in cancer depending on cellular context and tissue origin." (PMID 37667739, 2023). "Several studies also report that SIRT1 activation in cancer models results in clinical benefits." (PMID 37715252, 2023). "Furthermore, curcumin has been found to support metabolic activity and muscle force gain in models of cancer-induced cachexia and disuse muscle atrophy, where increased SIRT1 activity is observed." (PMID 37630770, 2023). "Collectively, in cancer cells, SIRT1 and c-Myc could form a positive feedback loop, in which activation of c-Myc increases the expression and activity of SIRT1 to deacetylate c-Myc." (PMID 37554307, 2023). "Interestingly, in cancer cells, we observed that SIRT1 inhibition, or the replacement of SIRT1 with an active site mutant, resulted in a higher induction of R-loops than a complete depletion of the SIRT1 protein." (PMID 37998365, 2023). "Furthermore, disruption of SUMOylation by targeting either Ubc9 or PIAS4 restored SIRT1 expression and favored an epithelial-like phenotype of cancer cells, thus preventing metastasis." (PMID 37670258, 2023). "Consistent with this, in cancer cells, although the total levels of R-loops in the rDNA coding region were not affected by SIRT1 activity, a loss of SIRT1 activity exhibited an increased frequency of replication-specific R-loops." (PMID 37998365, 2023). "The link between SIRT1 and c-Myc was first observed in cancer cells." (PMID 37554307, 2023). "According to the cellular environment, SIRT1 may act as both a tumor suppressor and a tumor promoter and may have different signaling targets in different cancer types." (PMID 37190306, 2023). "SIRT1, as a member of the NAD+ protein family, is involved in diverse biological events, including life-span extension, cellular senescence, age-related disorders, obesity-associated disease, heart disease, inflammation, and cancer." (PMID 37583461, 2023). "In addition, UA downregulated NF-κB and STAT3 phosphorylation levels after activating SIRT1, and these two pathways play a key role in regulating cancer cachexia." (PMID 37190306, 2023).
cancer (continued). "One of the processes regulated by this SIRT1/FoxO1 pathway is autophagy, which has emerged as a crucial and controversial mechanism that can play a dynamic tumor-suppressive or promoting role depending on the cancer context and cellular type." (PMID 36771230, 2023). "However, considerable evidence suggests that in a variety of malignant cell types, SIRT1 is upregulated and that SIRT1 antagonists prevented the development of cancer cells." (PMID 38283900, 2023). "The remission effect of SIRT1 activation on cancer cachexia models could be reversed by the inhibitor of SIRT1, Ex-527." (PMID 37190306, 2023). "Therefore, the results show that UA alleviates cancer cachexia and prevents muscle wasting by activating SIRT1 and inhibiting NF-κB and STAT3." (PMID 37190306, 2023). "Furthermore, 9 out of 11 poorly differentiated (G3) carcinomas (81.81%; mean IR score = 3.00 ± 0.713, range 0–6) stained only weakly for SIRT1, though moderate immunostaining was present in the phenotypically less aggressive counterparts." (PMID 37627400, 2023). "Interesting, some miRNAs can regulate the expression of SIRT1 to change the cancer cells growth." (PMID 35212616, 2022). "To investigate whether the PTM of FOXK2 affected chemosensitivity to cisplatin in cancer cells, we treated H1299 cells with the SIRT1 selective inhibitor EX527." (PMID 34866322, 2022). "There are seven different subtypes (SIRT1–7), which mainly regulate the expression of multiple genes through acetylation of proteins and participate in the pathogenesis of many chronic diseases such as diabetes, cardiovascular diseases, and cancer." (PMID 35350833, 2022). "Finally, the upregulation of SIRT1 mRNA expression significantly correlates with cellular oxidation, fibrosis, and apoptosis in cancer cells treated with curcumin." (PMID 36143462, 2022). "Sirt1 plays multiple roles in cancer and age-related diseases." (PMID 35163314, 2022). "Among the seven human sirtuins (SIRT1-7), a growing body of evidence suggests that SIRT1 modulates many signaling pathways by deacetylating substrate proteins involved in metabolic diseases, neurodegeneration, cancer and inflammation, thus linking SIRT1 to several diseases." (PMID 35337137, 2022). "However, in cancer cells and upon persistent stress signals, SIRT1 is overexpressed and consequently promotes DNA repair, leading to additional DNA mutations, and increasing genomic instability." (PMID 36361680, 2022). "Importantly, SIRT1 is upregulated in several cancers, including leukemia, lymphoma, soft-tissue sarcomas, prostate cancer, lung and colon carcinomas, non-melanoma skin cancers, and more." (PMID 35163511, 2022). "However, SIRT1 overexpression in tumor cells correlates with the silencing of tumor suppressor genes and cancer resistance to chemotherapy." (PMID 36009340, 2022). "Similarly, resveratrol acted as a redox regulator, remarkably decreasing OS levels and inhibiting cancer development through activating sirtuin 1 (SIRT1) and lncRNA-modulated pathways." (PMID 35081965, 2022). "While SIRT1 stimulates cell growth and proliferation in a variety of cancer subtypes, it may also act as a tumor suppressor." (PMID 35054489, 2022). "Testing of these two hypotheses may provide a more complete understanding of how SIRT1 is regulated and how it in turn regulates its downstream targets, which will be valuable in the design of new anti-cancer therapies." (PMID 35069908, 2022).